LINC01038 (long independently transcribed non-coding RNA 1038)
Gene: Long non-coding RNA gene on chromosome 13 (79,804,309 to 79,805,689, forward strand). Ensembl gene ENSG00000229011.
Diseases named in the same sentence as LINC01038 in open-access papers:
LINC01038 is named in the same sentence as 1 disease in open-access papers, as found by Europe PMC text mining. Sharing a sentence is not in itself a finding about the gene and the disease.
LINC01038 shares sentences with these, for which no sentence is quoted: schizophrenia (1 paper).